CASP8 (caspase 8)
Description:
Thiol protease that plays a key role in programmed cell death by acting as a molecular switch for apoptosis, necroptosis and pyroptosis, and is required to prevent tissue damage during embryonic development and adulthood. Initiator protease that induces extrinsic apoptosis by mediating cleavage and activation of effector caspases responsible for FAS/CD95-mediated and TNFRSF1A-induced cell death. Cleaves and activates effector caspases CASP3, CASP4, CASP6, CASP7, CASP9 and CASP10. Binding to the adapter molecule FADD recruits it to either receptor FAS/TNFRSF6 or TNFRSF1A. The resulting aggregate called the death-inducing signaling complex (DISC) performs CASP8 proteolytic activation. The active dimeric enzyme is then liberated from the DISC and free to activate downstream apoptotic proteases. Proteolytic fragments of the N-terminal propeptide (termed CAP3, CAP5 and CAP6) are likely retained in the DISC. Also cleaves and activates BID, thereby promoting cytochrome C release from mitochrondria (By similarity). In addition to extrinsic apoptosis, also acts as a negative regulator of necroptosis: acts by cleaving RIPK1 at 'Asp-324', which is crucial to inhibit RIPK1 kinase activity, limiting TNF-induced apoptosis, necroptosis and inflammatory response. Also able to initiate pyroptosis by mediating cleavage and activation of gasdermin-C and -D (GSDMC and GSDMD, respectively): gasdermin cleavage promotes release of the N-terminal moiety that binds to membranes and forms pores, triggering pyroptosis. Initiates pyroptosis following inactivation of MAP3K7/TAK1 (By similarity). Also acts as a regulator of innate immunity by mediating cleavage and inactivation of N4BP1 downstream of TLR3 or TLR4, thereby promoting cytokine production (By similarity). May participate in the Granzyme B (GZMB) cell death pathways. Cleaves PARP1 and PARP2. Independent of its protease activity, promotes cell migration following phosphorylation at Tyr-380. [Isoform 5]: Lacks the catalytic site and may interfere with the pro-apoptotic activity of the complex. [Isoform 6]: Lacks the catalytic site and may interfere with the pro-apoptotic activity of the complex. [Isoform 7]: Lacks the catalytic site and may interfere with the pro-apoptotic activity of the complex (Probable). Acts as an inhibitor of the caspase cascade. [Isoform 8]: Lacks the catalytic site and may interfere with the pro-apoptotic activity of the complex.
Synonyms: CASP-8; FLICE; MACH; MCH5; ALPS2B; CAP4
Tractability: Small molecule: a drug acting on it is in phase 2 or 3 trials; a structure with a bound ligand is known; a high-quality ligand is known; it has a high-quality binding pocket; it belongs to a druggable protein family. Antibody: its Gene Ontology location is reachable by antibodies, with medium confidence. PROTAC: ubiquitination databases record sites on it; its protein half-life has been measured; a small molecule that binds it is known.
Target class: Cysteine protease; Protease; Cysteine protease CD clan; Enzyme; Cysteine protease C14 family
Chemical probes: PD088650, PD088687, PD088689, PD088691, PD088712, PD088720
Gene: Protein-coding gene on chromosome 2 (201,233,443 to 201,361,836, forward strand). Ensembl gene ENSG00000064012.
Subcellular location: Cytoplasm; Nucleus; Cell projection, lamellipodium
Subcellular location (Human Protein Atlas): Cytosol; Mitochondria; Centriolar satellite; Connecting piece; Mid piece; Principal piece
Pathways (Reactome):
Programmed Cell Death: Activation, myristolyation of BID and translocation to mitochondria; Apoptotic cleavage of cellular proteins; Apoptotic execution phase; CASP8 activity is inhibited; Caspase activation via Death Receptors in the presence of ligand; Caspase-mediated cleavage of cytoskeletal proteins; Dimerization of procaspase-8; RIPK1-mediated regulated necrosis; Regulation by c-FLIP; Regulation of necroptotic cell death
Immune System: CLEC7A/inflammasome pathway; NF-kB activation through FADD/RIP-1 pathway mediated by caspase-8 and -10; NOD1/2 Signaling Pathway; Regulation of NF-kappa B signaling; TLR3-mediated TICAM1-dependent programmed cell death; TRIF-mediated programmed cell death
Signal Transduction: FasL/ CD95L signaling; Regulation of TNFR1 signaling; TNFR1-induced proapoptotic signaling; TRAIL signaling
Disease: Defective RIPK1-mediated regulated necrosis; Microbial modulation of RIPK1-mediated regulated necrosis
Gene Ontology:
Molecular function: cysteine-type endopeptidase activity; death effector domain binding; identical protein binding; peptidase activity; protein binding; scaffold protein binding; ubiquitin protein ligase binding; cysteine-type peptidase activity; cysteine-type endopeptidase activator activity involved in apoptotic process; death receptor binding; endopeptidase activity; protein-containing complex binding
Biological process: apoptotic process; apoptotic signaling pathway; cellular response to mechanical stimulus; execution phase of apoptosis; extrinsic apoptotic signaling pathway; extrinsic apoptotic signaling pathway via death domain receptors; negative regulation of canonical NF-kappaB signal transduction; negative regulation of necroptotic process; positive regulation of canonical NF-kappaB signal transduction; positive regulation of cell migration; positive regulation of execution phase of apoptosis; positive regulation of interleukin-1 beta production; positive regulation of macrophage differentiation; positive regulation of proteolysis; protein catabolic process; protein maturation; proteolysis; response to tumor necrosis factor; TRAIL-activated apoptotic signaling pathway; angiogenesis; B cell activation; death-inducing signaling complex assembly; heart development; macrophage differentiation; natural killer cell activation; and 21 more
Cellular component: caspase complex; CD95 death-inducing signaling complex; cytoplasm; cytosol; death-inducing signaling complex; lamellipodium; protein-containing complex; ripoptosome; cytoskeleton; mitochondrial outer membrane; mitochondrion; nucleus; cell body; Noc1p-Noc2p complex; plasma membrane
Genetic constraint (gnomAD): Loss-of-function variants: 20 observed, 41.8 expected, observed/expected ratio (o/e) 0.48, 90% interval 0.34 to 0.69. The upper end of that interval is the gene's LOEUF score, 0.69, which puts it in group 2 of 6, group 1 being the genes least tolerant of losing a copy. Missense variants: 415 observed, 519.33 expected, observed/expected ratio (o/e) 0.8, 90% interval 0.74 to 0.87. Synonymous variants: 168 observed, 188.11 expected, observed/expected ratio (o/e) 0.89, 90% interval 0.79 to 1.01.
Gene-disease validity (ClinGen):
ClinGen rates the evidence that CASP8 causes each of these diseases.
autoimmune lymphoproliferative syndrome type 2B (autosomal recessive): Definitive. Autoimmune lymphoproliferative syndrome (ALPS) with recurrent viral infections is a rare genetic disorder characterized by lymphadenopathy and/or splenomegaly and recurrent infections due to herpes viruses.
Cancer hallmarks: proliferative signalling (promotes); angiogenesis (promotes); tumour promoting inflammation (suppresses); invasion and metastasis (suppresses); invasion and metastasis (promotes); tumour promoting inflammation (promotes or suppresses); escaping programmed cell death (suppresses)
Homologues: Orthologues: chimpanzee CASP8 (99% identical), macaque CASP8 (94% identical), dog CASP8 (78% identical), pig CASP8 (74% identical), mouse Casp8 (67% identical), guinea pig CASP8 (66% identical), rat Casp8 (66% identical), Caenorhabditis elegans ced-3 (22% identical), Caenorhabditis elegans csp-1 (19% identical), Drosophila melanogaster Decay (19% identical), Caenorhabditis elegans csp-2 (19% identical), Drosophila melanogaster Dronc (19% identical), and 1 more. Paralogues in human: CASP10 (38% identical), CFLAR (24% identical), CASP7 (22% identical), CASP3 (22% identical), CASP9 (22% identical), CASP2 (20% identical), CASP6 (19% identical), CASP1 (18% identical), CASP5 (15% identical), CASP4 (15% identical), CASP12 (14% identical), CASP14 (14% identical), and 4 more.
Diseases named in the same sentence as CASP8 in open-access papers:
CASP8 is named in the same sentence as 448 diseases in open-access papers, as found by Europe PMC text mining. Sharing a sentence is not in itself a finding about the gene and the disease. The quoted sentences say what the papers report.
breast carcinoma (265 papers, 2006 to 2026). "To determine the effects of depleting the two rs3769823 A-risk allele-specific binding proteins on CASP8 transcription in melanoma, primary melanocyte cultures, and breast cancer cell lines, we knocked these genes down using siRNAs." (PMID 41542517, 2026). "One such insertion in an intron of the CASP8 gene was associated with an increased risk of breast cancer and abnormal splicing of CASP8 transcripts." (PMID 40510242, 2025). "CASP8 showed the most significant statistical association with breast cancer risk, especially within 5 years before cancer diagnosis, consistent with findings from the KARMA study in Sweden12." (PMID 40665092, 2025). "The investigations in breast carcinoma and prostate cancer have implicated the His variant of CASP8, D302H (rs1045485) as a protective risk allele." (PMID 41373475, 2025). "While our results strongly support the protective effect of elevated CASP8 protein levels against breast cancer risk, the literature presents contrasting findings." (PMID 39351539, 2024). "Inherited genetic variations in the CASP8 gene have also previously been found to be associated with breast cancer as well as other types of cancers." (PMID 38135714, 2024). "Our preliminary SMR analysis and validation MR analysis both supported the protective role of elevated CASP8 levels against breast cancer risk." (PMID 39351539, 2024). "Previous studies have also suggested that the CASP8 D302H polymorphism decreases breast cancer risk associated with BRCA1 and BRCA2 mutations, delaying cancer onset." (PMID 39351539, 2024). "Metformin activates caspase-3, which then activates caspase-8 and causes apoptosis in breast cancer cells." (PMID 37893061, 2023). "In this regard, haplotype analysis indicated combinations of multiple loci of CASP8, including a 3-SNPs, a 4-SNPs, and a 5-SNPs haplotypes, associated with 58–78% increased risk of breast cancer in the study population." (PMID 37016353, 2023). "Ferulic acid-mediated apoptosis was evaluated in MCF-7 breast cancer cells where it caused both caspase-8 and -9 activation." (PMID 36675194, 2023). "CASP8, as a key element of apoptosis, has been represented with several genomic variations in association with breast cancer." (PMID 37016353, 2023). "Our results indicate variations in CASP8 are associated with the risk of breast cancer as well as clinicopathological features." (PMID 37016353, 2023). "The present study suggests a diagnostic and prognostic role of CASP8 gene variations in breast cancer." (PMID 37016353, 2023). "CASP8, one of the first low penetrance loci, has been identified to be associated with the risk of breast cancer in candidate gene studies." (PMID 37016353, 2023). "The hypermethylation of Caspase-8 promoter and the subsequent loss of Caspase-8 expression have been reported in medulloblastoma, neuroblastoma, cervical cancer, breast cancer and glioblastoma." (PMID 37444381, 2023). "In two previous studies considering different polymorphisms of CASP8, several haplotypes, including rs7608692, rs3834129, rs3817578, and rs1045485, have been reported to be associated with a 28–31% increased risk of breast cancer." (PMID 37016353, 2023). "Our findings are in line with where the authors show that the strongest associations with breast cancer risk in the region come from variant rs1830298 and that variant rs3769821 is an eQTL for CASP8." (PMID 35061909, 2022). "In the 24 known breast cancer risk SNPs, rs1045485 in CASP8 was only found in Family 2 and was shared by the proband and the proband’s sister." (PMID 35625741, 2022). "The insertion of full-length SINE-VNTR-Alu retrotransposons (SVT) into intron 8 of the caspase-8 gene (CASP8) is associated with an increased risk of basal cell carcinoma and breast cancer but reduces the risk of prostate cancer." (PMID 34830126, 2021).
breast carcinoma (continued). "As the critical factor in the course of extrinsic apoptosis, CASP8 was demonstrated to exhibit a potential relationship with breast cancer risk, clinicopathological features, and prognostic outcomes of breast cancer from prior cohort-based analyses 17-19." (PMID 33403050, 2021). "The second largest subnetwork (13 nodes) contained the two breast cancer susceptibility genes CASP8 and BLM (Section 2.6)." (PMID 33735170, 2021). "In breast cancer, the administration of Walterinnesia aegyptia venom has been linked with apoptosis restoration via up-regulating caspase-3, caspase-8, and caspase-9." (PMID 33167431, 2020). "A few SNPs other than rs6760993 in CASP8 are previously associated with subtype-specific breast cancer risk." (PMID 33112566, 2020). "The other polymorphism, namely CASP8 Asp302His, is part of the coding region of caspase 8, causes an aspartic acid to histidine substitution and was likewise associated with decreased breast cancer susceptibility." (PMID 31467295, 2019). "Further, a polymorphic SVA E insertion within intron 8 of the CASP8 gene, tagged by the variant rs700635 (C), has been associated with CASP8 splicing abnormalities, as well as increased risk of cutaneous basal cell carcinoma and breast cancer." (PMID 31783611, 2019). "Based on the assumption that this polymorphism has an immunomodulatory role, it was further reported that the CASP8 -652Del variant significantly decreases breast cancer susceptibility in healthy individuals." (PMID 31467295, 2019). "Considering an immunomodulatory role of these polymorphisms, we genotyped 785 early breast cancer patients and correlated caspase 8 variants with disease-free survival (DFS) and the presence of tumor infiltrating lymphocytes (TILs)." (PMID 31467295, 2019). "Conclusively, we report that CASP8 302 HisHis variant is significantly associated with a tumor phenotype of low immune infiltration in the pooled patient cohort and among luminal breast cancer patients alone (by trend)." (PMID 31467295, 2019). "The association of CASP8 with breast cancer depended on BRCA1/BRCA2 mutation carrier status in some studies, but not others." (PMID 30601841, 2019). "Accordingly, deficiency of Casp8 facilitates cellular transformation in vitro, acts as driver mutation in breast cancer and B cell lymphoma, and is frequently found to be mutated in hepatocellular carcinomas and advanced gastric cancer." (PMID 30598363, 2019). "In conclusion, we show that the CASP8 -652 deletion is an allele-dose dependent prognostically favorable factor for DFS in breast cancer and that homozygosity for the -652Del variant is an independent predictor for improved DFS." (PMID 31467295, 2019). "Our data so far indicates, that loss of PAR-4 interferes with the activation of caspase-8 in breast cancer cells after stimulation with Etoposide." (PMID 31217499, 2019). "In cancer type stratification analysis, the CASP8 -652 6N ins/del polymorphism decreased risk for colorectal cancer, breast cancer, esophageal cancer, renal cell carcinoma, lung cancer, cervical cancer, bladder cancer, gastric cancer, and other cancers." (PMID 28915630, 2017). "So the insertion of full-length SVA (SINE-VNTR-Alu human retrotransposons) into intron 8 of the caspase 8 (CASP8) gene is associated with cutaneous basal cell carcinoma and breast cancer." (PMID 28222152, 2017). "In 2014, breast cancer- and colorectal cancer-specific meta-analyses concluded that the CASP8 -652 6N del polymorphism reduced cancer risk." (PMID 28915630, 2017). "The strongest gene–environment interaction in relation to overall breast cancer risk was noted between rs7558475 located in the CASP8 and FADD like apoptosis regulator (CFLAR) gene and current smoking (pint = 1.8 × 10−4)." (PMID 28670784, 2017). "While our results for CASP8 SNPs should be validated in other cohorts with subtype-specific information, we conclude that some SNPs in CASP8 are associated with subtype-specific breast cancer risk." (PMID 26758508, 2016).